CUL3 (cullin 3)
Diseases named in the same sentence as CUL3 in open-access papers (continued):
Sharing a sentence is not in itself a finding about the gene and the disease.
serous ovarian tumors (1 paper, 2014). "In conclusion, we have identified an extremely high frequency of genetic disruption affecting the KEAP1/CUL3/RBX1 E3-ubiquitin ligase complex in serous ovarian tumors, occurring predominantly through copy-number loss of RBX1." (PMID 25114896, 2014).
steatosis (1 paper, 2025). Increased lipid within the cytoplasm of cells. "The authors reported that NRF2 activation as a result of hepatocyte-specific knockout of cullin 3 results in rapid resolution of steatosis in obese mice, confirming various other studies." (PMID 40209947, 2025). "However, resolving steatosis in hepatocyte Cul3 KO mice did not lead to overall metabolic improvement but caused liver pathology and systemic metabolic changes, including hepatic ceramide accumulation, elevated circulating fatty acid levels, and systemic insulin resistance." (PMID 40209947, 2025).
Ureteral obstruction (1 paper, 2019). Obstruction of the flow of urine through the ureter. "Furthermore, following unilateral ureteral obstruction (UUO) or nephrotoxic nephritis (NTN), tubules with less CUL3 signal were surrounded by α-SMA+ areas." (PMID 30872636, 2019).
Uterine leiomyoma (1 paper, 2022). The presence of a leiomyoma of the uterus. "In this study, we have identified a novel uterine leiomyoma subtype with biallelic mutations in genes involved in neddylation of the Cullin 3-RING E3 ligase." (PMID 36068196, 2022). "While cancers frequently harbor loss-of-function mutations in KEAP1 and CUL3 or gain-of-function mutations in NFE2L2 (encoding NRF2) itself, no such mutations have been detected in uterine leiomyomas." (PMID 36068196, 2022).
vitiligo (1 paper, 2025). Generalized well circumscribed patches of leukoderma that are generally distributed over symmetric body locations and is due to autoimmune destruction of melanocytes. "Consequently, we were unable to evaluate whether the changes in CUL3 or NRF2 expression are dynamically linked to therapeutic outcomes in vitiligo patients over time." (PMID 40723924, 2025). "This study investigates CUL3, NRF2, and the associated regulatory networks in vitiligo, integrating clinical profiling and computational docking to identify therapeutic targets." (PMID 40723924, 2025). "Conversely, CUL3 expression showed a weak negative correlation with VASI (r = –0.305, p = 0.7), which may reflect the proposed oxidative stress-related impairment of the Keap1–NRF2–CUL3 pathway in vitiligo." (PMID 40723924, 2025). "Dysregulation of CUL3-mediated ubiquitination may, therefore, contribute to the pathogenesis of vitiligo by altering the degradation dynamics of key regulatory proteins, such as NRF2." (PMID 40723924, 2025). "The study’s findings of reduced CUL3 and NRF2 expression in vitiligo tissues align with the concept that the Keap1/CUL3/NRF2 axis is disrupted, impairing the cellular antioxidant response and predisposing melanocytes to oxidative damage." (PMID 40723924, 2025). "In summary, the present integrative analysis highlights the central roles of CUL3, NRF2, miRNA-146a, and Foxp3 in the pathogenesis of vitiligo, linking oxidative stress and immune dysregulation to melanocyte loss." (PMID 40723924, 2025). "In this study, the authors aim to comprehensively profile the expression of CUL3 and key regulatory molecules, including NRF2, NF-κB, miRNA-146a, and Foxp3, in patients with vitiligo, integrating clinical, in silico docking, and bioinformatics analyses." (PMID 40723924, 2025). "The relative expression levels of CUL3 and NRF2 were significantly downregulated in vitiligo patients compared to healthy controls, with mean ± SD values of 0.27 ± 0.03 and 0.37 ± 0.26, respectively, versus 1 ± 0.58 (p = 0.013)." (PMID 40723924, 2025). "The Keap1/NRF2/ARE pathway is critical for melanocyte protection against oxidative damage; however, the role of Cullin-3 (CUL3), a scaffold for E3 ubiquitin ligases that regulate NRF2 degradation, and its interplay with inflammatory mediators in vitiligo pathogenesis are underexplored." (PMID 40723924, 2025).
cancer (85 papers, 2013 to 2026). A tumor composed of atypical neoplastic, often pleomorphic cells that invade other tissues. "Dysfunctions in CUL3 have been linked to various malignant tumors, suggesting that E3 ubiquitin ligases can be explored as new targets for targeted cancer therapy." (PMID 38383403, 2024). "Remarkably, the Cul3 mutation stimulated cancer progression mainly by altering the immune microenvironment, whereas other mutations promoted the cell cycle." (PMID 38212325, 2024). "The accumulation of Nrf2 within cancer cells, along with its cytoprotective effects, can be attributed to somatic mutations in Nrf2, Keap1, or CUL3." (PMID 39872524, 2024). "Recent studies have reported that KEAP1/NFE2L2/CUL3 mutated in many cancers and led to worse survival outcomes in many cancers, our survival analysis also confirmed this." (PMID 34617407, 2021). "The interactions between Nrf2 and Keap1 are inhibited by somatic mutations acquired in the Nrf2, CUL3 and/or Keap1 genes in cancer cells." (PMID 33050575, 2020). "While the cullin 3 complex (CRL3) is more typically associated with cancer phenotypes, there is little data on the function of CRL5 in tumorigenesis or resistance." (PMID 31294695, 2019). "While CUL3 is implicated in a wide array of cancer biologies, relatively little is known about the physiological functions of many CUL5-containing ubiquitin ligases." (PMID 31294695, 2019). "Alterations of signaling pathways caused by the deregulation of CUL3 and/or CUL3-associated factors can give rise to cancer." (PMID 29594129, 2018). "In recent years, frequent mutations in the NFE2L2/KEAP1/CUL3 pathway had been reported in many types of cancers, including ESCC10,18–21." (PMID 29127303, 2017). "Mutation or deletion of CUL3, or methylation of its promoter, have been reported to occur at high frequencies in certain cancers." (PMID 27824809, 2016). "Notably, Kelch ECH-associated protein 1 (Keap1) and the speckle-type POZ protein (SPOP) are recognized as cancer-associated adaptors of CUL3, exerting pivotal roles in tumor progression." (PMID 37906282, 2023). "The most connected gene was CUL3, a regulator of several genes linked to cancer progression." (PMID 33735170, 2021). "We next investigated if the Cul3 deficiency in cancer cells could elicit any effects on tumor microenvironment (TME)." (PMID 34803491, 2021). "The CRL3-KEAP1-NRF2 pathway contributions to cancer development are reinforced by the observed deregulation of KEAP1 and the presence of CUL3 mutations that could lead to NRF2 overexpression in many cancers (Chen and Chen, 2016 and references therein)." (PMID 29594129, 2018). "A protein-truncating CUL3 mutation was found in one cancer (P16)." (PMID 25790038, 2015). "Thanks to their smaller size and network structure, they provided compelling hypotheses on genes like COPS5 and CUL3, which lack genome-wide association with the disease but are related to cancer at the expression level and consistently interact with high scoring genes." (PMID 33735170, 2021). "Similar to DI-591, DI-404 effectively and selectively blocks UBE2M-DCN1 interaction and CUL3 neddylation in several cancer cell lines." (PMID 41540013, 2026). "In human cancers of the lung, esophagus, head and neck, liver, and bladder, high levels of NRF2 activating mutations, NRF2 copy number amplifications or KEAP1/CUL3 loss-of-function mutations are observed." (PMID 40027760, 2025). "The Cancer Genome Atlas consortium and other sequencing projects have found that the KEAP1-NRF2 degradation pathway is frequently altered in cancer, by either gain-of-function mutations in NRF2 or loss-of-function mutations in KEAP1 or CUL3." (PMID 40470216, 2025). "Genetic alterations are a major driver of NRF2 dysregulation in cancer, particularly mutations in KEAP1, NFE2L2 (NRF2), and CUL3, which disrupt KEAP1-mediated ubiquitination and lead to constitutive NRF2 stabilization." (PMID 41470226, 2025).
cancer (continued). "Given the known functions of PRKAG1-interacting proteins (e.g., BCDIN3D, KBTBD4, CUL3) in cell cycle regulation, we evaluated the association between PRKAG1 expression and cancer-related pathways using gene set variation analysis (GSVA)." (PMID 40958861, 2025). "Independently of KEAP1/NRF2/CUL3 mutations, altered protein-protein interactions and KEAP1-inactivating posttranslational modifications also activate NRF2 in cancer, most notably in tissues of the liver, breast and kidney." (PMID 40027760, 2025). "A comprehensive genomic analysis of squamous cell lung cancers revealed that 34% of these cancers harboured somatic mutations in NFE2L2 (19%), KEAP1 (12%) or CUL3 (7%), resulting in the downregulation of NRF2 repressors and activation of NRF2." (PMID 37047696, 2023). "CUL3 is an E3 ubiquitin ligase, an essential executor for regulating protein homeostasis in cancer development." (PMID 37723559, 2023). "CUL3 is a ubiquitin ligase, involved in different diseases, such as muscle and metabolic dysfunctions, but also in cancers." (PMID 35409691, 2022). "Gain-of-function mutations in NFE2L2, loss-of-function mutations in key members of the KEAP1/CUL3/RBX1 E3-ubiquitin ligase complex, and succination of KEAP1 have proven to activate the NRF2 pathway in many cancer types." (PMID 36068196, 2022). "Recently, it has been demonstrated that phosphorylation of PD-L1 at Thr285 and Thr290 by CK2 disrupted PD-L1 binding with speckle-type POZ protein and protected PD-L1 from cullin 3 ubiquitin E3 ligase complex-mediated proteasomal degradation in cancer and DC." (PMID 36009534, 2022). "Although large-scale genomic studies have identified the frequent mutations in KEAP1/NRF2/ CUL3 pathway and their prominent roles in LUSC and other cancers, less attention is paid on their complicated down-stream effects." (PMID 32434476, 2020). "An increase of Nrf2 pathway activation, resulting from the disruption of KEAP1/CUL3/RBX1 E3-ubiquitin ligase complex is observed in many cancers and potentially leads to chemoresistance." (PMID 32346533, 2020). "Recent studies have firmly established that SPOP is a substrate-specific adaptor that binds Cul3 and exerts cancer-promoting or cancer-suppressive effects depending on the specific substrate in various cancers." (PMID 30607139, 2018). "In particular, Keap1, KLHL20, and SPOP are the most reported Cul3 substrate adaptors for their impacts on various cancer types." (PMID 27200299, 2016). "In this review, we will discuss recent advances on the functions of Cul3 ubiquitin ligases in cancer development, progression, and therapeutic response and the dysregulation of Cul3-mediated ubiquitination events in human malignancies." (PMID 27200299, 2016). "Likewise, NAcM-OPT, an orally bioavailable inhibitor with satisfactory solubility and permeability, selectively decreases CUL1 and CUL3 neddylation levels and restrains cancer hallmarks in the squamous cell carcinoma line." (PMID 41540013, 2026). "Targeting the COX-2/exo-miR-1290/CUL3/Nrf2 signal pathway might be a novel, stroma-focused, cancer prevention or treatment strategy." (PMID 37723559, 2023). "Additionally, CUL3 overexpression in fibroblasts suppressed COX-2 exosomes-mediated cancer cell proliferation and invasion, in addition to ECM production and EMT process, and finally repressed tumor progression in vivo." (PMID 37723559, 2023). "We utilized multilevel TCGA data to investigate whether somatic mutations in UBE2M, NAE1, NEDD8, or the NEDD8-binding domain of CUL3 can be found in cancers with NRF2 activation." (PMID 36068196, 2022). "Recently it has been demonstrated that the CK2-dependent phosphorylation of PD-L1 at positions Thr285 and Thr290 disrupted PD-L1 binding with speckle-type POZ protein and protected PD-L1 from cullin 3 ubiquitin E3 ligase complex-mediated proteasomal degradation in cancer and dendritic cells (DC)." (PMID 36009534, 2022).
cancer (continued). "SPOP acts as a substrate adaptor for the Cullin 3‐based ubiquitination and is involved in epigenetic control and regulation of the cell cycle, such that SPOP mutation is associated with pathogenesis of a number of cancers." (PMID 34586738, 2021). "Therefore, our future efforts will focus on verifying the effect of the CUL3/KCTD5-mediated regulation of RhoGDI1 stability on cancer progression." (PMID 32876072, 2020). "Similarly, the generated Keap1 and/or CUL3 mutants in cancer cells prevent CUL3–Keap1–Nrf2 complex formation, blocking Nrf2 ubiquitination." (PMID 33050575, 2020). "In particular, we will focus on three Cul3 substrate adaptors, kelch-like ECH-associated protein (Keap1), kelch-like family member 20 (KLHL20), and speckle type BTB/POZ protein (SPOP), with the intent to highlight novel targets in cancer therapy." (PMID 27200299, 2016). "Although the full list of targets whose ubiquitination and degradation is mediated by Cul3 remains unknown, cancer-related proteins reported include cyclin E, or Rho, among others." (PMID 23308193, 2013). "Neddylation and deneddylation may regulate Cul3 protein accumulation, suggesting new approaches to treat cancer by inhibiting the NEDD8-activated-cullin ligases." (PMID 23308193, 2013). "Cul3 was uncovered as a clinically and biologically relevant candidate, which could promote cancer aggressiveness by regulating the expression of other critical cancer-related proteins." (PMID 23308193, 2013). "This revealed 11 samples across six different cancer types with a nonsynonymous mutation in a neddylation-associated gene: four with a UBE2M mutation, five with a NAE1 mutation, one with a NEDD8 mutation, and one with a mutation in the NEDD8-binding domain of CUL3." (PMID 36068196, 2022). "Target genes of miR-576 (CUL3 and RAC1) have been identified to be involved in the regulation of multiple cancer-related biological pathways, and the target genes of miR-616 (ASB13 and FBXW2) have been reported to be associated with the development of other cancers." (PMID 35008363, 2021). "Genetic alterations in KEAP1, NRF2, and CUL3 such as somatic mutations, copy number variations, and epigenetic changes are the major reasons for the gain-of-function and aberrant activation of NRF2-regulated pathways in human cancers and are often correlated with poor prognosis and survival." (PMID 31884422, 2019). "In addition, systematic identification and characterization of substrates of these three adaptors and other Cul3 substrate adaptors can potentially facilitate a more comprehensive understanding on the functions of Cul3 ubiquitin ligases in cancer biology and their clinical implications." (PMID 27200299, 2016). "Interestingly, genes such as CCDC88C, CD200R1, and CUL3 have been associated with prognosis or being highly expressed in other forms of cancer, however they have not been reported in PDAC to the best of our knowledge." (PMID 25180633, 2014). "In cancer cells, cyclin D–CDK4/6-dependent phosphorylation of speckle-type POZ protein (SPOP)/Cullin-3 ubiquitin ligase complex destabilizes PD-L1 via proteasome-mediated degradation, but inhibition of CDK4/6 significantly elevates PD-L1 level." (PMID 39103548, 2024). "For example, cullin 3 (CUL3)-mediated beclin 1 (BECN1) degradation inhibits autophagy and promotes cancer progression." (PMID 37394582, 2023). "CUL3 and CUL7 are members of the Cullin ubiquitin ligase family and are involved in the regulation of various cancer-related biological pathways." (PMID 35463358, 2022). "The zero-order network of proteins upregulated in advanced GC centers on cullin-3 (CUL3), which is part of the ubiquitin–proteasome system controlling many physiological processes, including cancer." (PMID 35566209, 2022). "In proteins homologous to PfK13 such as the KEAP1 protein, whose dysfunction is involved in certain cancers, the BTB domain mediates varying oligomerization architectures and interacts with the cullin-3 ubiquitin ligase." (PMID 34606334, 2022).
cancer (continued). "Furthermore, one substrate adaptor of CUL3, kelch-like ECH-associated protein (Keap), was first identified as an inhibitor of transcriptional factor Nf-E2-related factor 2 (Nrf2) and played important roles in anti-oxidation stress and cell defense during cancer suppression." (PMID 32170141, 2020). "For example, CUL3, in complex with the substrate adaptor Ketch-like family member 20 (KLHL20), is thought to promote cancer progression through increased ubiquitination and degradation of the Promyelocytic leukemia (PML) protein." (PMID 29594129, 2018). "The data showed that inhibition of miR-7641 upregulated RPS16 in all cancer cell lines, while TNFSF10, RNF4, EMC8 and CUL3 responded irregularly." (PMID 28827731, 2017). "The disruption of this partnership involving the ubiquitination of NFE2L2 through the KEAP1/CUL3/RBX1 complex and its posterior proteasomal degradation, which leads to the constitutive activation of antioxidant response genes is known in several cancer types." (PMID 26792175, 2016). "Independent of KEAP1/NRF2/CUL3 mutations, altered protein-protein interactions and KEAP1-inactivating posttranslational modifications also activate NRF2 in cancer, most notably in tissues of the liver, breast, and kidney." (PMID 40889681, 2025). "In addition, decreased expression of KLF5 (cancer stage II), KLHL13 (stages III and IV), and CUL3 (stages II and IV) correlated with advanced tumor staging." (PMID 41443421, 2025). "However, the expressions of CUL3, GSK3B, KEAP1, and MAPK9 showed positive relationship with RNAss in various cancers." (PMID 35242279, 2022). "While sub-micromolar concentrations of DI-591 were able to inhibit the NEDDylation of Cullin-3 in cancer cells, it did not display any cytotoxic properties in concentrations up to 20 μM." (PMID 34209641, 2021). "Moreover, PD-L1 abundance fluctuates during cell cycle progression in various cancer cell lines, which is regulated by cyclin D-CDK4 and cullin 3-SPOP E3 ligase via proteasome-mediated degradation." (PMID 33557163, 2021). "While not profound in fold-change, the expression of CUL3 was largely downregulated in cancer vs. normal with significant down-regulation in five TCGA groups: KIRC, KICH, KIRP, HNSC, and BLCA." (PMID 30647843, 2018). "We identified damaging mutations in ATR, BRCA1/2, MAP4K1, CUL3 and MAX, already reported in other cancer types but not described yet as mutated in PTC." (PMID 25803323, 2015). "In addition to proteins known to directly bind REN, such as Cul3, RBX1, and KCTD15, we recovered various potential REN interactors including SALL4, a cell stemness regulator aberrantly activated in several types of human cancers." (PMID 38062245, 2024). "Compared to Del-c1 and c3, the majority of cancer genes were deleted by DEL-c2, such as CDKN2A (207/528), FHIT (133/528), KDM6A (42/528), RB1 (27/528), FAT1 (23/528), NFE2L2 (13/528), ERBB4 (20/528), CUL3 (11/528), PTEN (9/528), ZNF750 (13/528) and NOTCH1 (8/528)." (PMID 36272974, 2022). "For the positive–negative subjects (screening), 3 CNAs were detected in BC genes (ACVR2A, CUL3 and PIK3R1), and 5 SNPs were identified in 6 non-BC cancer genes (SNIP1, TBC1D10B, PANK1, PRKCA and RUNX2; SUPT3H)." (PMID 35589867, 2022). "However, depletion of Cullin 3, but not Cullin 1, elevated the protein abundance of endogenous HDAC6 in multiple cancer cell lines including HT29, HCT116, PC3, and HeLa." (PMID 28599312, 2017).